KL (klotho)
Diseases named in the same sentence as KL in open-access papers (continued):
Sharing a sentence is not in itself a finding about the gene and the disease.
cardiovascular disease (105 papers, 2012 to 2025). "Previous studies have shown that Klotho deficiency accelerates age-related phenotypes, including cardiovascular disease, neurodegeneration, and renal dysfunction." (PMID 40894259, 2025). "Although there are many studies on the increased risk of cardiovascular disease in AS patients, there have been few studies examining the relationship between Klotho levels and parameters such as SCORE and AI (Atherosclerotic Index) in AS patients." (PMID 41517379, 2025). "This study aimed to investigate the association between soluble Klotho (sKlotho) levels and cardiovascular disease (CVD) events, fractures, and all-cause mortality in this population." (PMID 41141519, 2025). "In terms of genetic predisposition to cardiovascular diseases, the polymorphism of the Klotho gene has been associated." (PMID 41517379, 2025). "The combination of elevated FGF23 and Klotho deficiency contributes to cardiovascular diseases in patients with CKD." (PMID 38792509, 2024). "On the other hand, plasma klotho is independently associated with cardiovascular disease in adults and a cardioprotective role of klotho has already been described." (PMID 38541889, 2024). "On the other hand, certain interventions can be used clinically to reduce Ca+2, PO-4, GAL-3 and increase the content of Klotho, thereby reducing the risk of cardiovascular diseases in patients with CKD." (PMID 37492290, 2023). "Higher Klotho levels are associated with a lower cardiovascular risk, thereby suggesting a possible protective role for Klotho in cardiovascular diseases." (PMID 37242170, 2023). "In the clinical context, reduced levels of Klotho have been related to an increased risk for cardiovascular diseases, supporting its proposal as a predictor of all-cause mortality in the elderly." (PMID 35042527, 2022). "A large amount of evidence has shown that the deletion of the anti-aging gene Klotho (KL) is associated with the development of a variety of cardiovascular diseases." (PMID 35721561, 2022). "Klotho deficiency is a significant predictor of cardiovascular disease (CVD)-related mortality and morbidity." (PMID 36221064, 2022). "All in all, the information previously presented highlights the association between Klotho and cardiovascular disease in CKD—a common complication that often contributes to mortality in patients with CKD." (PMID 35056905, 2021). "A deregulation of the klotho/FGF23 state observed in CKD has also been linked with cardiovascular disease such as left ventricular hypertrophy, vascular calcification, and endothelial dysfunction." (PMID 32570781, 2020). "A Spanish study found association between the vascular levels of Klotho expression and presence of cardiovascular disease and cardiovascular risk factors." (PMID 32444684, 2020). "The association between serum Klotho and the classic risk factors, as well as the clinical history of cardiovascular disease, was also shown." (PMID 30671457, 2018). "In favor of a rationale that supports the compensatory action of Klotho, an association between serum Klotho level and classic risk factors, as well as a clinical history of cardiovascular diseases, has also been investigated." (PMID 30671457, 2018). "Many studies showed that Klotho deficiency or KLOTHO gene polymorphism can be the risk factors for the most prevalent cardiovascular diseases." (PMID 30671457, 2018). "On this basis, there is a deep suggestion that depletion of Klotho can promote prooxidative, proinflammatory, and proapoptotic activity in cardiomyocytes, leading to their damage in patients at higher risk of cardiovascular diseases." (PMID 30671457, 2018). "Genetic studies have shown that Klotho gene variants are associated with atherosclerotic disease, and only one study reported a significant correlation between Klotho plasma levels and a reduction in the risk of cardiovascular disease (CVD)." (PMID 30547758, 2018).
cardiovascular disease (continued). "In this work, we have tested the influence of Klotho gene variants on Klotho gene expression levels in human vascular tissue and their association with cardiovascular disease and cardiovascular risk factors." (PMID 26538295, 2016). "Serum soluble Klotho (sKlotho) also possibly plays a role in determining the risk of cardiovascular disease or mortality in some populations and animal models." (PMID 26604925, 2015). "Single nucleotide polymorphisms of the human klotho gene are associated with the development of cardiovascular diseases in both Chinese Han and Caucasoid subjects." (PMID 24683546, 2014). "The discovery that Klotho is also expressed in peripheral arterioles has led to the hypothesis that it may be linked to cardiovascular diseases." (PMID 39940672, 2025). "Klotho decreases with age and Klotho deficiency is known to be associated with vascular calcification, impaired angiogenesis and vasculogenesis, and loss of arterial wall elasticity, which contributes to increased blood pressure and cardiovascular diseases." (PMID 40943475, 2025). "Another potential mechanism may be through increasing serum klotho levels, and higher serum klotho levels are associated with a lower risk of cardiovascular disease." (PMID 38791238, 2024). "Moreover, age-adjusted serum Klotho levels are inversely correlated with the risk of cardiovascular disease (P < .001)." (PMID 38213484, 2024). "Therefore, research on the potential therapeutic roles of klotho in oncology, renal and cardiovascular diseases is emerging, and some beneficial effects of treating klotho deficiency have been observed in animal models." (PMID 37693344, 2023). "They reported a mutant Klotho-deficient animal model, which presented phenotypes similar to age-related events in humans, such as reduced lifespan, alongside vascular calcification and cardiovascular disease." (PMID 35056905, 2021). "Furthermore, elevated levels of soluble Klotho in plasma are independently associated with a lower risk of cardiovascular disease." (PMID 33585584, 2020). "Notably, homozygous expression of the KL-VERSUS variant has resulted in a lower secretion of klotho as compared with the heterozygous expression of this klotho variant, leading to cardiovascular disease." (PMID 32570781, 2020). "Decrease in soluble anti-aging Klotho protein levels is associated to cardiovascular disease (CVD)." (PMID 31986490, 2020). "Moreover, several clinical studies have observed that lower systemic levels of the soluble form of Klotho are associated with markers of vascular dysfunction as well as with the prevalence and severity of cardiovascular disease (CVD)." (PMID 31986490, 2020). "In the present proof‐of‐concept study we aimed to evaluate the genetic contribution of the Klotho KL‐VS and G‐395A variants to the incidence of cardiovascular disease, its relationship with cardiovascular risk factors, and the influence in the expression level of this gene in human aortic samples." (PMID 26538295, 2016). "The primary aim of this proof‐of‐concept study was to analyse the existence of a potential link between Klotho gene polymorphisms and the expression level of this gene in the vascular wall, and additionally with the incidence of cardiovascular disease and cardiovascular risk factors." (PMID 26538295, 2016). "In human population studies, genetic variants in the KL gene have been associated with longevity and several age-related disorders, such as cardiovascular disease and its associated risk factors and cognitive function, all of which are consistent with its association with life span." (PMID 24036517, 2013). "Klotho exerts protective effects in diabetes, cardiovascular diseases, and neurodegenerative disorders." (PMID 41002407, 2025). "Researchers are working to determine the functions of Klotho and how it contributes to the dysfunction of the most common illnesses, including cardiovascular diseases (CVD)." (PMID 40119098, 2025).
cardiovascular disease (continued). "This work enriches our comprehension of statin capabilities and underscores the critical roles of pluripotency genes and klotho in cardiovascular disease progression." (PMID 38610757, 2024). "Cr, Ca+2 and PO-4 are risk factors for CKD complicated with cardiovascular disease, while Klotho is a protective factor for cardiovascular disease." (PMID 37492290, 2023). "Treatment with klotho protein promoted cardiomyocyte viability and metabolic activity, supporting klotho and KL as a feasible direction of therapy in some cardiovascular diseases." (PMID 37008065, 2023). "Counterintuitively, serum Klotho was positively associated with the occurrence and severity of CAD in the group of subjects with T2DM, independently of traditional risk factors for cardiovascular disease." (PMID 37686263, 2023). "Exploring concrete mammalian models (mostly mouse models) of aging-related diseases has revealed the therapeutic effect of enhancing KL expression in neurodegenerative diseases, chronic kidney diseases, cardiovascular diseases, etc." (PMID 37008065, 2023). "For this reason, Klotho can be considered a potential protective factor in cardiovascular diseases as well." (PMID 37985893, 2023). "Between mineral bone disturbances in CKD patients, increased fibroblast growth factor (FGF) 23 and decreased Klotho are emerging as important effectors of cardiovascular disease." (PMID 35042527, 2022). "In this study, we introduced the cardiovascular disease-related suppressor protein klotho as a positive control." (PMID 36120595, 2022). "A case–control study with a designated experimental group of 110 patients with histories of cardiovascular disease (CVD) showed that s-Klotho levels were significantly lower in the CVD group and inversely correlated with CRP and TNFα/IL10." (PMID 35603960, 2022). "Logistic regression results for relationship between Klotho (log2 transformation) and specific cardiovascular disease (CVD)." (PMID 35509269, 2022). "In previous studies, when patients with cardiovascular disease were compared with healthy individuals, there were differences in S-Klotho plasma levels in 45 pg/ml (626 and 671 pg/ml, respectively)." (PMID 35619959, 2022). "Logistic regression results for relationship between Klotho and specific cardiovascular disease (CVD)." (PMID 35509269, 2022). "The in vivo pharmacokinetics and binding efficiency of CFNs to atherosclerotic plaques were evaluated using the cardiovascular disease-related suppressor protein klotho as a positive control." (PMID 36120595, 2022). "Discussions of SHPTH need to consider fibroblast growth factor-23 (FGF23) and klotho to form accurate assessments of links to important outcomes such as cardiovascular disease." (PMID 33022030, 2021). "Klotho and FGF-23 have been already associated with cardiovascular disease mortality in patients with CKD." (PMID 33160321, 2020). "Our results are in line with previous findings in the literature that point to soluble Klotho as a protective factor against cardiovascular disorders." (PMID 31986490, 2020). "Klotho and its protective effect against IR can be considered as a preventive and therapeutic factor for cardiovascular disease and attenuating factor of ischemic-reperfusion injury, which can be increased by exercise training." (PMID 31096903, 2019). "Conversely, expression of Klotho was reduced in patients with cardiovascular disease when comparing to controls." (PMID 31542779, 2019). "Understanding the mechanism of Klotho protection can provide information on the most prevalent disorders, such as cardiovascular disease." (PMID 30671457, 2018). "It is also well established that Klotho plays an important role in the prevention of cardiovascular diseases, particularly in the maintaining of appropriate cardiac and vascular function." (PMID 30671457, 2018).
cardiovascular disease (continued). "Taking into account the fact that Klotho is involved in a resistance to oxidative stress, some scientists have focused on the role of Klotho in the development of cardiovascular diseases." (PMID 30671457, 2018). "Klotho protects against development of multiple age-related disorders, including cardiovascular diseases." (PMID 30595559, 2018). "A rapidly increasing body of evidence supports involvement of the fibroblast growth factor 23 (FGF23)-klotho-vitamin D axis in the pathogenesis of cardiovascular disease in CKD patients." (PMID 26807718, 2016). "Recent translational reports have described the existence of FGF23-Klotho axis in the vasculature and the causative effect of FGF23 on cardiovascular disease." (PMID 24678415, 2014). "In humans, low serum Klotho levels are related to the prevalence of cardiovascular diseases in community-dwelling adults." (PMID 23431388, 2013). "In the following section, the authors will discuss the protective roles of Klotho in the kidney, lung, brain, liver, and peripheral blood vessels (including cardiovascular diseases), which are key organs affected by dysfunctional disorders in age-related diseases and preeclamptic pregnancy." (PMID 39940672, 2025). "Klotho may also reduce the expression of pro-inflammatory factors and may be important in the Klotho-IL-10-eosinophils pathway in patients with cardiovascular diseases." (PMID 41574188, 2025). "Klotho seems to be a promising parameter in the context of cardiovascular diseases." (PMID 38787156, 2024). "However, till now, such an association was only confirmed in patients with established cardiovascular disease (CVD), whose low Klotho concentrations accompanied low IL-10 levels." (PMID 36362746, 2022). "Therefore, the underlying mechanism responsible for the direct effect between Klotho and cardiovascular disease (CVD) remains to be elucidated." (PMID 35509269, 2022). "Additionally, studies have discovered that decreased soluble Klotho levels are related to left ventricular hypertrophy, myocardial fibrosis, and the prevalence of cardiovascular disease." (PMID 35509269, 2022). "Preserved Klotho expression may support cardiovascular protection and serve as a prognostic tool and therapeutic target for cardiovascular diseases." (PMID 32319182, 2020). "Conclusively, it appears plausible that an activity of Klotho could be protective in a damaged myocardial tissue and open new path for the treatment of cardiovascular diseases." (PMID 30671457, 2018). "Recently, experiments described Klotho’s involvement in cancer and cardiovascular diseases." (PMID 26452228, 2015). "Cardiovascular disease is the primary cause of mortality in kidney-related illnesses patients, and meta-analysis study offers an in-depth and extensive examination of the relationship between Klotho levels and negative cardiovascular results." (PMID 40119098, 2025). "Therefore, declines in circulating Klotho may precede the onset of cardiovascular disease with aging, which further supports the use of Klotho as a potential biomarker of cardiovascular disease." (PMID 38036596, 2023). "In addition, the reduction in Klotho is associated, as shown by different studies and with some of the characteristics of CKD, such as cellular senescence, albuminuria and cardiovascular disease." (PMID 35056905, 2021). "Since Klotho deficiency is a condition associated with different pathological scenarios, such as CKD or cardiovascular disease, it would be interesting to perform studies that investigate the possible association of this and other non-functional variants of the KL gene with these diseases." (PMID 31013726, 2019). "Thus, the antioxidative and antiapoptotic activity of Klotho could be considered as the novel protective factor in cardiovascular disease and heart injury." (PMID 30671457, 2018).
cardiovascular disease (continued). "Furthermore, the Klotho protein was considered as a regulator of cardiovascular disease, and the progress of kidney dysfunction decreases Klotho gene expression, which might in turn impair calcium and phosphate metabolism and cell function." (PMID 29329323, 2018). "We analysed other biomarkers that, in recent years, have been related to cardiovascular disease, such as suPAR, FABP4, and MM biomarkers (P, PTH, vitamin D, FGF-23, klotho)." (PMID 39940753, 2025). "Crucially, abnormal levels and activity of Klotho and FGF23 are highly related to cardiovascular disease (CVD)." (PMID 41574188, 2025). "At the same time, some studies have found that Klotho, FGFR1, and FGFR3 are expressed in the vascular wall, which suggests that the vascular wall is the target organ of FGF23, and also that FGF23 is involved in the occurrence and development of cardiovascular diseases." (PMID 39096857, 2024). "Therefore, taking into account the fact that the development of cardiovascular disease in ESRD patients is common, Klotho protein could provide the protection of vasculature and cardiac tissue." (PMID 30671457, 2018). "Similarly, there was an association between plasma Klotho and CVD in fifty healthy volunteers without any known risk factors for cardiovascular disorders." (PMID 30671457, 2018). "However, the expression levels of Klotho in acute cardiovascular disease have not been reported." (PMID 39330350, 2024).